PDE4D (phosphodiesterase 4D)
Diseases named in the same sentence as PDE4D in open-access papers (continued):
Sharing a sentence is not in itself a finding about the gene and the disease.
COVID-19 (4 papers, 2021 to 2023). A disease caused by infection with severe acute respiratory syndrome coronavirus 2. "PDE4D gene, which plays an important role in the immune signaling pathway, was highly expressed in heart tissue of COVID-19 patients." (PMID 37762464, 2023). "We believe that the combination of PDE4D inhibitor and vitamin C is a potential drug combination for the treatment of COVID-19, especially in severely ill patients." (PMID 35071229, 2021). "GSE151879 data showed that PDE4D was highly expressed in the heart tissues of patients with COVID-19, especially in hESC-derived cardiomyocytes." (PMID 35071229, 2021). "In particular, we found a common gene, PDE4D, in all three warning models, and PDE4D are highly expressed in the heart tissue from patients with COVID-19, especially in hESC-derived cardiomyocytes." (PMID 35071229, 2021). "Another interesting compound is quercetin, a naturally derived PDE4 (Phosphodiesterase 4D)-selective inhibitor found in fruits, vegetables, and tea, with antioxidant and anti-inflammatory properties, which has been proposed in the treatment of COVID-19." (PMID 34440765, 2021). "We speculated that the PDE4D could be a potential drug therapeutic target of COVID-19, especially for critical patients." (PMID 35071229, 2021). "We found a potential target for the COVID-19 besides the known targets, such as the PDE4D." (PMID 35071229, 2021).
glioblastoma (4 papers, 2013 to 2021). The most malignant astrocytic tumor (WHO grade IV). "However, CG500354, which targets the specific variant PDE4D, may provide a closer step in solving the therapeutic issues of aggressive glioblastoma." (PMID 24989033, 2014). "In another study, PDE4D was demonstrated to be abundantly expressed in glioblastoma cells and its inhibitor Rolipram was found to induce tumor regression." (PMID 24989033, 2014). "On the other hand, alterations of SGCG, HTR4, ITGB1, CPS1, PROS1 and INPP5A were detected predominantly in anaplastic astrocytoma, while alterations of PDE4D were present in both glioblastoma subtypes." (PMID 24358143, 2013). "Furthermore, the expression of several PDEs is upregulated in glioblastoma cells, and the specific isoforms PDE1C, PDE4A, PDE4B, PDE4D and PDE5 have been suggested as therapeutic targets in glioblastoma." (PMID 34575827, 2021).
glioma (4 papers, 2013 to 2026). A benign or malignant brain and spinal cord tumor that arises from glial cells (astrocytes, oligodendrocytes, ependymal cells). "And the target genes for SOX2 binding regions in glioma cells were identified, such as ARRDC4, PDE4D, BASP1 and so on." (PMID 24565222, 2013). "PDE4D was changed in 9 out of 30 patients (30%) and distributed almost equally in grade III and grade IV glioma (25% vs. 31.8% respectively)." (PMID 24358143, 2013).
hepatocellular carcinoma (4 papers, 2021 to 2024). A malignant tumor that arises from hepatocytes. "Isoform D of type 4 phosphodiesterase (PDE4D) has recently been associated with several human cancer types with the exception of human hepatocellular carcinoma (HCC)." (PMID 34062786, 2021). "PDE4D overexpression increases the dephosphorylation and activity of YAP, promoting the growth of hepatocellular carcinoma cells in vitro and in vivo." (PMID 38903532, 2024).
Insulin resistance (4 papers, 2021 to 2024). Increased resistance towards insulin, that is, diminished effectiveness of insulin in reducing blood glucose levels. "High expression of PDE4D exacerbates hepatic lipid deposition and insulin resistance, subsequently promoting the secretion of TGF-β1 into blood, which leads to kidney damage." (PMID 37072403, 2023). "In turn, hepatic overexpression of PDE4D resulted in renal injury accompanied by hepatic insulin resistance and moderate systemic insulin resistance." (PMID 37072403, 2023). "In addition, we found that PDE4D, which affects the development of insulin resistance in obesity, was positively correlated with BMI." (PMID 38555350, 2024). "It has been observed that PDE3A, PDE3B, PDE4B, PDE4D, and PDE8B in rat islets and in INS-1E cells activate multiple signal pathways critical for pancreatic beta cell function, and their abnormalities are associated with insulin resistance." (PMID 35046895, 2021). "Interestingly, the phosphodiesterase IV (PDE4D) inhibitor roflumilast has been reported to ameliorate the symptoms of T2DM and insulin resistance by potentiating cAMP signaling, possibly influencing insulin secretion." (PMID 39458839, 2024). "Given that PDE4D expression increased only in the liver in HFD mice, these findings indicated that PDE4 inhibitors might restore kidney function partially by improving hepatic insulin resistance but not insulin resistance in other tissues." (PMID 37072403, 2023).
leukemia (4 papers, 2021 to 2024). A malignant (clonal) hematologic disorder, involving hematopoietic stem cells and characterized by the presence of primitive or atypical myeloid or lymphoid cells in the bone marrow and the blood. "Among them, PDE4D has been reported to act as a proliferation promoter in several different tumors, and mutations in SERP2 are associated with leukemia." (PMID 34565479, 2021).
medulloblastoma (4 papers, 2015 to 2024). A malignant, invasive embryonal neoplasm arising from the cerebellum. "In mouse medulloblastoma allografts, PDE4D inhibitors suppress Hh transduction and inhibit tumor growth." (PMID 26371509, 2015). "Among these validated targets, Pde1c may be involved in Hh signaling regulation, as the phosphodiesterase family protein PDE4D is known to enhance Hh signaling activity by inhibiting PKA in human medulloblastoma cells." (PMID 35573695, 2022). "Pituitary adenylyl cyclase inhibits the proliferation of medulloblastoma cells through PKA-Gli1 pathway, and neurociliary proteins inhibit the growth of medulloblastoma through PDE4D-PKA-Hedgehog pathway." (PMID 33292604, 2020). "Here we show that phosphodiesterase 4D (PDE4D) acts downstream of Neuropilins to control Hh transduction and medulloblastoma growth." (PMID 26371509, 2015).
pseudohypoparathyroidism (4 papers, 2020 to 2025). "ASD has since been reported as a phenotypic feature of acrodysostosis type 2 (associated with PRKAR1A and PDE4D genes) and pseudohypoparathyroidism (associated with GNAS gene)." (PMID 40917827, 2025). "Genetic evaluation revealed a variant in PDE4D and subsequent pseudohypoparathyroidism." (PMID 32993552, 2020).
pulmonary fibrosis (4 papers, 2023 to 2025). Chronic progressive interstitial lung disorder characterized by the replacement of the lung tissue by connective tissue, leading to progressive dyspnea, respiratory failure, or right heart failure. "In addition, PDE4B shows higher expression levels in the lung compared with PDE4D and has been implicated in the development of pulmonary fibrosis, whereas PDE4D expression is elevated in the liver under pathological conditions, as shown in this study, thereby promoting liver fibrosis." (PMID 41196648, 2025).
Sepsis (4 papers, 2021 to 2023). Sepsis is defined as life-threatening organ dysfunction caused by a dysregulated host response to infection. "The study found that the low level of PDE4D expression was associated with HLA-DMA and HLA-DMB, while PDE4D expression continued to decline over time in sepsis patients." (PMID 34484417, 2021). "In patients with sepsis who exhibited features of immune depression, inverse correlations between HLA-DR (including HLA-DMA and HLA-DMB) and PDE4D expression were observed, indicating the role of cAMP-related HLA-DR modulation in sepsis." (PMID 37033939, 2023). "The expression of PDE4D in sepsis patients decreased continuously with time, and the low expression level of PDE4D was found to be related to HLA-DMA and HLA-DMB." (PMID 37834169, 2023). "Understanding the effect of phosphodiesterase 4D in regulating cardiac responsiveness to dobutamine may provide the potential of a PDE4D targeted therapy for sepsis patients with low cardiac output requiring inotropic support in future." (PMID 34758739, 2021).
cardiac hypertrophy (3 papers, 2010 to 2025). "We generated global and conditional cardiac-specific heterozygous PDE4D knockout mice and adeno-associated virus serotype 9-PDE4D overexpression to determine the role of PDE4D in cardiac hypertrophy and HF." (PMID 40015131, 2025). "In vivo, ISO injection or TAC inhibited cardiac mitophagy and caused cardiac hypertrophy and HF, which were ameliorated by roflumilast or cardiac-specific PDE4D haploinsufficiency." (PMID 40015131, 2025). "PDE4D isoforms are associated with the cardiac βAR signaling and prevent catecholamine-induced cardiac hypertrophy." (PMID 37971403, 2024). "Our study showed that PDE4D is a novel driver of oxidative stress and cardiac hypertrophy by reducing mitophagy through inhibition of CREB-SIRT1 signaling, which is opposite to the protective effects of PDE4B in HF." (PMID 40015131, 2025). "Collectively, these results suggest that cardiac-specific PDE4D haploinsufficiency plays a protective role against TAC-induced cardiac hypertrophy and HF." (PMID 40015131, 2025). "Conversely, cardiac PDE4D overexpression suppressed cardiac mitophagy and abolished the protective effects of global PDE4D haploinsufficiency on TAC-induced cardiac hypertrophy and HF." (PMID 40015131, 2025). "Our data are consistent with those results and show moreover that this PDE4D decrease occurs at a very early stage in the development of cardiac hypertrophy." (PMID 21151982, 2010). "PDE4D inhibition by rAAV9 injection or the pharmacological inhibitor roflumilast shows protection against cardiac hypertrophy and dysfunction through promoting cAMP, cAMP response element binding (CREB), and NAD-dependent deacetylase sirtuin 1 signaling for SERCA2a expression." (PMID 37971403, 2024). "Together, these results are consistent with the cardioprotective effects of roflumilast, suggesting that reducing the abundance of PDE4D may provide an effective strategy to protect against cardiac hypertrophy and mitochondrial dysfunction by modulating SIRT1-mediated mitophagy." (PMID 40015131, 2025). "To further investigate the role of PDE4D5 in pathological cardiac hypertrophy and HF in vivo, we performed an AAV9-mediated rescue experiment using heterozygous PDE4D global knockout mice (PDE4D+/−)." (PMID 40015131, 2025).
cardiomyopathy (3 papers, 2021 to 2025). A disease of the heart muscle or myocardium proper. "The current study identifies upregulation of specific PDE4D isoforms that selectively inhibit SERCA2a function in HFD-induced cardiomyopathy, indicating that this remodelling can be targeted to restore cardiac contractility in diabetic cardiomyopathy." (PMID 39662482, 2025).
colorectal tumor (3 papers, 2016 to 2025). "We detected the protein levels of PDE4D in normal tissue (NT), colorectal tumour tissue (CTT), and liver tumour tissue (LTT)." (PMID 39956959, 2025). "Furthermore, our analysis of human colorectal tumor specimens revealed significant inverse correlation between the expression of miR-139-5p and that of PDE4D." (PMID 27383270, 2016).
pancreatic cancer (3 papers, 2019 to 2024). "Given that PDE4D interacts with mTORC1 and promotes its activation by inhibiting PKA-mediated raptor phosphorylation at Ser-791, pharmacological inhibition of PDE4D by roflumilast or GEBR-7b suppresses pancreatic cancer cell growth in vitro and in vivo." (PMID 38233872, 2024). "In order to illuminate the effect of PDE4D on pancreatic cancer cells, cell migration and invasion assays were performed." (PMID 31772658, 2019). "PDE4D depletion significantly suppressed β-catenin and Snail expression as well as the migration and invasion abilities of pancreatic cancer cells." (PMID 31772658, 2019). "Mechanism by which PDE4D affects migration and invasion function of pancreatic cancer cells was further investigated." (PMID 31772658, 2019). "Pharmacologic PDE4D inhibition suppresses mTORC1 signaling and pancreatic cancer growth in vivo." (PMID 37427586, 2023). "Moreover, pancreatic cancer exhibits an upregulation of PDE4D expression, and high PDE4D levels predict the poor overall survival of patients with pancreatic cancer." (PMID 37427586, 2023). "Effect of PDE4D on pancreatic cancer cells was detected by cell migration and invasion assays." (PMID 31772658, 2019). "Moreover, PDE4D levels play a key role in the overall survival of patients with pancreatic cancer." (PMID 37427586, 2023). "Moreover, the level of PDE4D correlates with mTORC1 activity in pancreatic cancer cells." (PMID 37427586, 2023). "Interestingly, it appears that PDE4D regulates mTORC1 activity, cell size, and cell proliferation in KRAS-mutant (AsPC-1) compared with non–KRAS-mutant (BxPC-3) pancreatic cancer cells." (PMID 37427586, 2023).
pancreatic ductal adenocarcinoma (3 papers, 2019 to 2023). An infiltrating adenocarcinoma that arises from the epithelial cells of the pancreas. "We confirmed that PDE4D expression is higher in tissues of patients with pancreatic ductal adenocarcinoma (PDAC) compared with paired benign tissues." (PMID 37427586, 2023). "However, the expression and significance of PDE4D in pancreatic ductal adenocarcinoma (PDAC) have not been elucidated." (PMID 31772658, 2019).
prostate tumours (3 papers, 2015 to 2021). "Phosphodiesterase 4D (PDE4D) may induce PCa cell proliferation, and one recent study showed that PDE4D inhibitors reduce prostate tumor growth in animal models." (PMID 26692910, 2015).
aneurysm (2 papers, 2021 to 2023). Bulging or ballooning in an area of an artery secondary to arterial wall weakening. "Surprisingly, discrepant data has been recently published, reporting a significant increase in PDE4D expression in both human and experimental AAAs and that the specific deletion of PDE4D in VSMCs attenuates aneurysm formation in a mouse model." (PMID 38069339, 2023).
Anxiety (2 papers, 2015 to 2017). Intense feelings of nervousness, tension, or panic often arise in response to interpersonal stresses. "In addition, pde4d−/− mutants respond to the anxiogenic effects of rolipram, indicating that the targets of rolipram in anxiety are via other PDE4 subfamilies and not PDE4D." (PMID 26388333, 2015).
Arrhythmia (2 papers, 2024 to 2025). Any cardiac rhythm other than the normal sinus rhythm. "We could verify the direct impact of PDE4B and PDE4D deficiency on arrhythmia susceptibility by performing analysis of extra beats measurements of single CMs as well as by measuring arrhythmia occurrence in intact Langendorff perfused hearts, either at basal level or upon β-AR stimulation." (PMID 38534320, 2024). "This pathogenic mechanism is further highlighted by studies in PDE4D-deficient mice, where PKA hyperphosphorylation of RyR2 leads to increased susceptibility to exercise-induced arrhythmias and late-onset dilated cardiomyopathy." (PMID 40136709, 2025). "Here, we could detect a strong increase in ventricular tachycardia in PDE4B-KO hearts under ISO stimulation, as opposed to unchanged number of arrhythmias in PDE4D-KO hearts, at least under this stimulation protocol." (PMID 38534320, 2024).
carotid atherosclerosis (2 papers, 2010 to 2021). A thickening and loss of elasticity of the walls of carotid arteries that occur with formation of atherosclerotic plaques. "In humans, it has been shown that the correlation between PDE4D gene expression and carotid atherosclerosis (assessed by intima-media thickness and plaque index) exists only for men, not women." (PMID 35822023, 2021). "To clarify the influence of sex on the relationship between the PDE4D gene and carotid atherosclerosis, we first performed the analyses in the overall data and then analyzed the data from men and women separately." (PMID 20540798, 2010). "The main finding of the present study is to demonstrate the PDE4D effect on preclinical carotid atherosclerosis." (PMID 20540798, 2010).
cerebral infarction (2 papers, 2012 to 2014). An ischemic condition of the brain, producing a persistent focal neurological deficit in the area of distribution of the cerebral arteries. "The C allele frequency of the rs2910829 locus in the PDE4D gene of the cerebral infarction group (81.0%) was significantly higher than that of the control group (76.4%) (P<0.05)." (PMID 24348782, 2014). "Furthermore, the A allele frequency of the rs918592 locus in the PDE4D gene in the Uygur cerebral infarction group was significantly higher than that of the Uygur control group (P<0.05)." (PMID 24348782, 2014). "In addition, we did not study SNPs from other susceptible genes, e.g., phosphodiesterase 4D (PDE4D) in which some of the SNPs have been shown to be associated with the development of cerebral infarction." (PMID 22849376, 2012). "However, it was suggested that the C allele of the rs2910829 locus of the PDE4D gene may be a common allele indicating susceptibility for cerebral infarction in the Uygur and Han populations." (PMID 24348782, 2014). "In this study, case-control and molecular biology methods were combined to investigate the PDE4D gene in the patients with cerebral infarction in Xinjiang." (PMID 24348782, 2014). "A number of studies have suggested that the PDE4D gene is correlated with cerebral infarction in Asian, European and North American populations; however, other studies have indicated that these correlations do not exist." (PMID 24348782, 2014). "The results showed that the CC genotype of the rs2910829 locus of the PDE4D gene in Uygur and Han patients with cerebral infarction had the highest distribution frequency, while the frequency distribution of the C allele was higher than that of the T allele." (PMID 24348782, 2014). "The AG genotype of the rs918592 locus of the PDE4D gene in the Uygur and Han patients with cerebral infarction had the highest distribution frequency, which was consistent with the results from previous studies." (PMID 24348782, 2014). "In this study, the correlation between the single nucleotide polymorphisms (SNPs) at rs2910829 and rs918592 in the phosphodiesterase 4D (PDE4D) gene and cerebral infarction in the Uygur and Han ethnic groups of Xinjiang, China were examined." (PMID 24348782, 2014).
dementia (2 papers, 2020 to 2025). Loss of intellectual abilities interfering with an individual's social and occupational functions. "Further investigation of PDE4D as a therapeutic target for dementia would be valuable." (PMID 32471155, 2020).
esophageal cancer (2 papers, 2022 to 2025). A primary or metastatic malignant neoplasm involving the esophagus. "Conversely, downregulation of PDE4D expression was observed in esophageal cancer tissues, and it was found to bind with lncRNA MANCR promoting esophageal cancer cell proliferation and inhibiting cell apoptosis." (PMID 40129976, 2025).